CD3D (CD3 delta subunit of T-cell receptor complex)
Diseases named in the same sentence as CD3D in open-access papers (continued):
Sharing a sentence is not in itself a finding about the gene and the disease.
bladder cancer (6 papers, 2019 to 2023). "Previous research found that CD3D/CD4 ratio is an important marker for the prognosis of bladder cancer." (PMID 33204728, 2020). "For example, the downregulation of CD3D in bladder cancer samples and the T-cell receptors that are essential for the activation of T cell signaling, indicate a new therapeutic approach for bladder cancer." (PMID 31293967, 2019). "We computed the Pearson correlation of CD3D using 26,483 transcripts of 431 bladder cancer patients." (PMID 31293967, 2019).
severe combined immunodeficiency (5 papers, 2022 to 2024). Severe combined immunodeficiency (SCID) comprises a group of rare monogenic primary immunodeficiency disorders characterized by a lack of functional peripheral T lymphocytes resulting in early-onset severe respiratory infections and failure to thrive. "ABE has also demonstrated promising effectiveness in correcting mutations in CD3D causing severe combined immunodeficiency (SCID), and restoring normal expression of CD3δ, which is necessary for normal thymopoiesis." (PMID 38785523, 2024). "Severe combined immunodeficiency (SCID) caused by mutations in the CD3δ gene is a life-threatening congenital immune deficiency that results in a severe deficiency of T cells, typically leading to death during infancy." (PMID 39707395, 2024). "Finally, ABEs have been recently used for the targeted correction of CD3D C202T, a mutation causing CD3δ severe combined immunodeficiency (SCID) in Jurkat T-cells and in CD34+ HSPCs leading to a more efficient CD3 repair compared to a CRISPR-Cas9 correction via homologous recombination." (PMID 36553489, 2022).
cervical cancer (4 papers, 2022 to 2023). A primary or metastatic malignant neoplasm involving the cervix.
glioblastoma (4 papers, 2017 to 2023). The most malignant astrocytic tumor (WHO grade IV). "A set of glioblastoma (GB) 79 patients were selected from the TCGA database based on quality assessments, as well as the availability of T1-weighted-post-contrast, T2-FLAIR images and accompanying clinical and molecular data, specifically CD3D/E/G mRNA expression level data." (PMID 29254160, 2017).
glioma (4 papers, 2024 to 2025). A benign or malignant brain and spinal cord tumor that arises from glial cells (astrocytes, oligodendrocytes, ependymal cells). "CLIC4 expression levels were positively correlated with specific markers of macrophages (CD80, CD86, MRC1), neutrophils (FCGR3A, FCGR3B), eosinophils (SIGLEC8, IL3RA), T cells (CD3D, CD4), CD8+ T cells (CD8A, CD8D), NK cells (NCAM1), and B cells (CD19) in glioma." (PMID 39595145, 2024).
head and neck squamous cell carcinoma (3 papers, 2019 to 2025). A squamous cell carcinoma that arises from any of the following anatomic sites: lip and oral cavity, nasal cavity, paranasal sinuses, pharynx, larynx, and salivary glands. "The high expression of CD3D correlates with immune cell infiltration and with the response to immunotherapy in patients with head and neck squamous cell carcinoma and colon adenocarcinoma." (PMID 39339213, 2024).
liver cancer (3 papers, 2021 to 2025). An epithelial or non-epithelial malignant neoplasm that arises from the liver. "Previous studies have shown that CD3D is associated with prognosis and treatment response in breast, colorectal, and liver cancer." (PMID 35719985, 2022). "Immunohistochemical analysis of the protein expression levels of CD3D in and around carcinomas was performed in the liver cancer cohorts of the First Affiliated Hospital of China Medical University." (PMID 34124275, 2021). "The differences in protein levels of C1QC, CD3D, GZMA, and PSMB9 in different liver cancer stages were determined using immunohistochemistry." (PMID 34124275, 2021).
lung carcinoma (3 papers, 2022 to 2024). "Yet, the proportion of samples exhibiting high levels of both TYRP1 and CD3D samples was comparatively low in SKCM relative to the lung cancers." (PMID 39943991, 2024).
Primary immunodeficiency (3 papers, 2016 to 2022). "GSEA analysis adds more insight into the 23 ERBB2-related DEGs and primary immunodeficiency signaling pathway, showing that ERBB2-related DEGs associated with primary immunodeficiency were mainly down-regulated ERBB2-related DEGs, such as CD79A, CD19, CD3D, CD3E, CD8A, and CD4." (PMID 36437939, 2022). "Primary immunodeficiency was specifically inhibited (p = 0.0041), reflecting the up regulation of Cd8 (marker for cytotoxic T cells), Cd3δ, Cd3ε (required for differentiation of pro-T cells into pre-T cells) and Lck (required for Cd4+Cd8+ T cell differentiation into Cd8+ T cells)." (PMID 27515027, 2016).
seminoma (3 papers, 2023 to 2025). A radiosensitive malignant germ cell tumor found in the testis (especially undescended), and extragonadal sites (anterior mediastinum and pineal gland). "In line with the high inter-patient variation observed in our study, differential expression of CD3D, CD3E, and genes associated with TIL senescence were reported in two seminoma subtypes by other groups." (PMID 38649788, 2024). "To further examine the functions of MMP9 and CTSK in seminoma, we subset immune cells (PTPRC+), and explored the expression patterns of markers for T cells (CD3D+ and CD3E+) and B cells (CD79B+; MS4A1+ and SDC1+)." (PMID 38123589, 2023).
adult T-cell leukemia (2 papers, 2022). "This was the most notable gene cluster which included the genes CD3D, CD3E, and CD3G which are part of the KEGG pathway for Human T-cell Leukemia Virus type 1 (HTLV-I) infection (KEGG pathway hsa05166), and HTLV-I infections are a known risk factor for developing adult T-cell leukemia/lymphoma." (PMID 35927608, 2022). "Some examples, including ADA for adult T-cell leukemia (ATL), CD3D for T1DM and EPCAM for hepatitis C (HC), are known target–disease associations, indicating that our proposed method can accurately predict known therapeutic indications." (PMID 35758779, 2022).
aneurysm (2 papers, 2009 to 2023). Bulging or ballooning in an area of an artery secondary to arterial wall weakening. "RNA FISH indicated that a spot of cells coexpressing αSMA and CD68 and a spot of cells coexpressing αSMA and CD3D were present in the tunica media of aneurysm tissue, verifying the presence of macrophage-like VSMCs and T-cell-like VSMCs." (PMID 37189183, 2023). "Genes that can be considered as markers for the following cell types were upregulated in aneurysms: neutrophils (Csf3r); T lymphocytes (Cd3d) and B lymphocytes (Blnk, Cd72, various immunoglobulin genes); and monocyte/macrophages (Cd14, Cd68)." (PMID 19580648, 2009).
colon adenocarcinoma (2 papers, 2022 to 2024). "Low CD3D expression was correlated with increasing clinical stage in colon adenocarcinoma and its increased expression showed better clinical outcome." (PMID 36299526, 2022).
colorectal cancer (2 papers, 2022). A primary or metastatic malignant neoplasm that affects the colon or rectum. "In contrast, in patients with colorectal cancer, high CD3D expression was found to predict better clinical outcomes." (PMID 35719985, 2022). "ACTR3B (actin-related protein 3B) protein expression has been linked to colorectal cancer invasion and proliferation, it is part of a complex with CAPG and CD3D that interacts with several HIV proteins and its expression aids SARS-CoV-2 binding and intracellular processing." (PMID 36299731, 2022).
glomerulonephritis (2 papers, 2024 to 2025). A renal disorder characterized by damage in the glomeruli. "Glomerulonephritis samples additionally showed expression of collagen (COL1A1) and immune cell markers for monocytes or macrophages (LYZ and CD163) and T cells (CD3D, CD3E and CD3G)." (PMID 41028563, 2025).
liver fibrosis (2 papers, 2023 to 2025). "MF2 cells specifically expressed liver fibrosis-related genes AGTR1, CYGB, PIEZO2, and LPL, and MF5 cells specifically highly expressed immune-related genes TRAC, CD3D, GZMB, and FCGR3A." (PMID 40949143, 2025).
lymph node metastasis (2 papers, 2020 to 2022). "The T cell‐like B cells in GC was further confirmed in the metastatic lymph node LN2 and two new GC metastases we obtained (LN3 from the patient who had GC with lymph node metastasis; O2 from the patient who had GC with ovary metastasis) with the marker genes CD19 and CD3D." (PMID 35184420, 2022).
prostate carcinoma (2 papers, 2022). A carcinoma that arises from epithelial cells of the prostate gland. "Moreover, IFN-stimulated genes are significantly associated with CD8A and CD3D expression, indicating the correlation between the IFN signaling and T cells infiltration in prostate cancer samples." (PMID 35836810, 2022). "In this study, we performed gene expression analysis on peripheral blood from prostate cancer patients obtained post- radiotherapy and showed that 6 genes, including CCR7, FCGR2B, BTLA, CD6, CD3D, and CD3E, were down-regulated by a range of 1.5–2.5-fold as compared to pre-radiotherapy samples." (PMID 36291815, 2022). "In this study, we performed next-generation sequencing-based gene expression analysis in peripheral blood from prostate cancer patients obtained pre- and post-radiotherapy and found six independently down-regulated genes including CCR7, FCGR2B, BTLA, CD6, CD3D, and CD3E." (PMID 36291815, 2022).
rheumatoid arthritis (2 papers, 2021 to 2022). A chronic, systemic autoimmune disorder characterized by inflammation in the synovial membranes and articular surfaces. "It exists on the surface of T lymphocytes and plays an important role in the adaptive immune response.A bioinformatis study on the progression of rheumatoid arthritis has shown that CD3D is a potential key mediator and diagnostic marker." (PMID 36187128, 2022).
T-cell immunodeficiency (2 papers, 2021 to 2025). A broad classification of disorders that affect the cell-mediated aspect of the immune response. "Defects in CD3G are associated with T cell immunodeficiency, while CD3D is involved in T-cell development and signal transduction." (PMID 34367157, 2021). "CD3D mutations in T cells cause destructive immunity innate errors, while CD3G deletion leads to T cell immunodeficiency." (PMID 40697415, 2025).
aortic aneurysm (1 paper, 2022). A ruptured aneurysm located in the wall of the proximal portion of the descending aorta proceeding from the arch of the aorta. "T-cell-like VSMCs (αSMA + CD3D+) existed in the tunica media of aortic aneurysm but not in the normal aorta." (PMID 35837612, 2022).
asthma (1 paper, 2022). "Further, to explore the potential function of key hub genes in childhood asthma, we used GSEA to analyze enriched KEGG pathways in the samples with high CD3D or CD3G expression in the different datasets." (PMID 36118895, 2022). "To date, no studies have reported on the relationship between CD3D, CD3G, RGS1, HLA-DMB, GBP4, GBP5, and asthma." (PMID 36118895, 2022).
atrial fibrillation (1 paper, 2023). A disorder characterized by an electrocardiographic finding of a supraventricular arrhythmia characterized by the replacement of consistent P waves by rapid oscillations or fibrillatory waves that vary in size, shape and timing and are accompanied by an irregular ventricular response. "The dysregulation of Tfh (follicular helper T) cells induced by the interaction between CD48 and CD3D has been reported as a common pathogenic mechanism underlying the co-occurrence of dilated cardiomyopathy and atrial fibrillation." (PMID 37349706, 2023).
childhood asthma (1 paper, 2022). "Second, while preliminary analyses revealed potential correlations between two key hub genes (CD3D and CD3G) and childhood asthma, further in-depth study is required, and the corresponding results need to be verified by further biological experiments." (PMID 36118895, 2022). "Using the weighted gene co-expression network analysis (WGCNA), CD3D and CD3G were identified as key genes closely correlated with childhood asthma." (PMID 36118895, 2022). "Results showed that the mRNA levels of CD3D, CD3G, HLA-DMB, CD69, RGS1, and CIITA were significantly upregulated in childhood asthma patients compared with the control individuals." (PMID 36118895, 2022). "Results showed that the mRNA expression levels of CD3D, CD3G, HLA-DMB, CD69, RGS1, and CIITA were significantly upregulated in childhood asthma patients compared with healthy controls, consistent with bioinformatics analysis." (PMID 36118895, 2022). "Based on qRT-PCR validation, CD3D, CD3G, HLA-DMB, CD69, RGS1, and CIITA were shown to be upregulated in childhood asthma patients." (PMID 36118895, 2022). "Interestingly, by intersecting these 20 overlapped genes with all hub genes, CD3D and CD3G were selected as key hub genes highly correlated with childhood asthma." (PMID 36118895, 2022). "Moreover, using WGCNA, CD3D, and CD3G were identified as key hub genes closely correlated with childhood asthma." (PMID 36118895, 2022). "Thus, together with our results, we speculate that CD3D and CD3G may be functionally important for differentiation regulation of Th cell subsets in the process of childhood asthma." (PMID 36118895, 2022). "Moreover, we also found that CD3D and CD3G might be involved in differentiation regulation of Th cell subsets in the process of childhood asthma." (PMID 36118895, 2022).
chordoma (1 paper, 2023). Chordomas are rare malignant tumors arising from embryonic remnants of the notochord in axial skeleton. "Initially, we investigated the impact of FN1 on CD4 T cells and CD8 T cells by analysing the presence of CD3D, CD4, CD8 and FN1 in both primary and recurrent chordoma specimens." (PMID 37784253, 2023).
chronic graft versus host disease (1 paper, 2010). Chronic graft versus host disease (GVHD) is a complication that can occur after a stem cell or bone marrow transplant in which the newly transplanted donor cells attack the transplant recipient's body. "CD3D is a receptor involved in TCR activation which has been recently found to be a biomarker for chronic graft-versus-host disease in mononuclear cell samples from allogeneic hematopoietic stem cell transplantation recipients and primary Sjögren's syndrome." (PMID 21152067, 2010).
cognitive deficits (1 paper, 2022). "In the context of cognitive deficits after TBI, we found that several inflammations and immune-related genes (Mterf1a, Trp73, Cd3d, Dll1, and Il5) had abnormal expression levels lncRNAs may potentially target." (PMID 35311004, 2022).
depression (1 paper, 2022). "Furthermore, we discovered other target genes and drug repurposing candidates for depression, the efficacies of which are supported by published evidence; for example, muromanab, which targets CD3D/CD247, and taurine, which targets GABBR1." (PMID 36009493, 2022).
diabetic nephropathy (1 paper, 2025). "The expression levels of IL7R, CD2, GZMA, CD3D and FCER1A significantly differed between diabetic nephropathy and controls." (PMID 41332907, 2025).
eosinophilia (1 paper, 2025). "This latter study additionally showed that hyper-eosinophilia in 4-week-old IL-5 transgenic (CD3d-Il5; JAX#036943) mdx mice did not contribute significantly to muscle pathology." (PMID 39900735, 2025).
epilepsy (1 paper, 2025). A brain disorder characterized by episodes of abnormally increased neuronal discharge resulting in transient episodes of sensory or motor neurological dysfunction, or psychic dysfunction. "Currently, functional analysis of CD3D in epilepsy is limited, but CD3D has been found to be associated with immune checkpoints." (PMID 40697415, 2025). "CD3D is directly involved in T cell development, cell migration, and activation signaling pathways and is associated with propionate treatment resistance in epilepsy." (PMID 40697415, 2025). "Previous study reported that severe immunodeficient phenotype of epilepsy with deletion of CD3D and CD3G may cause defective T cell development and lead to the early onset of the disease." (PMID 40697415, 2025). "Among them, we observed that the levels of CD3D, CD3G, CTSW, and JCHAIN were all significantly downregulated in epilepsy samples in the GSE143272 and GSE32534 datasets." (PMID 40697415, 2025). "CD3D, CD3G, CTSW, and JCHAIN were consistently expressed in the GSE143272 and GSE32534 datasets and all showed a low expression in epilepsy samples." (PMID 40697415, 2025). "Integrated transcriptomic and single-cell sequencing analyses identified CD3D, CD3G, CTSW, and JCHAIN as the key epilepsy genes that were also closely related to T cell function." (PMID 40697415, 2025). "In our research, both CD3D and CD3G were downregulated in epilepsy samples." (PMID 40697415, 2025). "A total of nine hub genes were screened in this study, in particular, four hub genes (CD3D, CD3G, CTSW, and JCHAIN) could effectively distinguish epilepsy samples." (PMID 40697415, 2025). "Hence, we hypothesized that suppression of CD3D and CD3G expression limited T cell immune function and that impaired autoimmune function exacerbated the progression of epilepsy." (PMID 40697415, 2025). "Second, the specific mechanism of the roles of CD3D, CD3G, CTSW, and JCHAIN in the development of epilepsy has not been verified by cell or animal experiments." (PMID 40697415, 2025).
Epileptic encephalopathy (1 paper, 2018). A condition in which epileptiform abnormalities are believed to contribute to the progressive disturbance in cerebral function. "The top-ranked probes related to 25 genes including HNRNPL, RASSF5, CD3D and KALRN involved in immune signalling pathways, in addition to TBC1D24, FBXO9 and VIPR2 previously linked to epileptic encephalopathy." (PMID 29484035, 2018).
immunodeficiency type 19 (1 paper, 2020). "This young infant was diagnosed at six months of age with "immunodeficiency type 19" (MIM#615617) due to homozygous nonsense variant, NM_000732.4 (CD3D):c.128G > A, p.Trp43∗ (variation ClinVar#VCV000643120.1; pathogenic)." (PMID 33354374, 2020).
Mycobacterium infection (1 paper, 2021). Infections with bacteria of the genus Mycobacterium. "The role of the remaining 7 genes (CD2, CD6, CD247, ZAP70, CD3D, SH2D1A, and CD3E) in T-cell signaling and modulation of host immune responses in mycobacterium infections is also supported." (PMID 35198572, 2021).
Neonatal sepsis (1 paper, 2021). Systemic inflammatory response to infection in newborn babies. "Interestingly, we found that the promoters of genes involved in T-cell regulation (i.e., CD3D, CD3G, UBASH3A, SIT1, and TXK) were hypermethylated in neonatal sepsis compared to controls, thereby resulting in decreased expression." (PMID 33659006, 2021).
neuroblastoma (1 paper, 2026). Neuroblastoma (NB) is the most common solid, extracranial childhood tumor. "Six of these genes (CMBL, LY6E, KLRB1, CTSH, CD3D, and PTGDS) were utilized to construct a risk-scoring model that effectively stratified neuroblastoma patients into high- and low-risk groups with significantly distinct clinical outcomes (p < 0.001)." (PMID 41993132, 2026).
non-small cell lung carcinoma (1 paper, 2021). A group of at least three distinct histological types of lung cancer, including non-small cell squamous cell carcinoma, adenocarcinoma, and large cell carcinoma. "Similar to CD52, CD3D is differentially expressed in the normal and malignant lung tissues of non-small cell lung cancer, consistent with our prediction." (PMID 34575089, 2021).